LGMN (legumain)
Diseases named in the same sentence as LGMN in open-access papers (continued):
Sharing a sentence is not in itself a finding about the gene and the disease.
cancer (continued). "The miR-495-3p is a short-stranded RNA blocking post-transcriptional translation of legumain and is proposed as a biomarker in some cancer types." (PMID 36555634, 2022). "Legumain has been found overexpressed in several cancers, which serves as an important biomarker for cancer diagnosis." (PMID 35631369, 2022). "Overall, even though more studies are needed to address these issues, the current study is the first to demonstrate that legumain has a high potential to serve as a biomarker in dogs with cancers." (PMID 35203212, 2022). "Confocal studies clearly displayed the potential of [18F]SF-AAN for distinguishing legumain overexpressed cancers." (PMID 35631369, 2022). "Patients with higher Legumain expression were more likely to have higher carcinoma grade as well as carcinoma recurrence." (PMID 35813634, 2022). "Essentially, this notion is limited to findings showing that cathepsin B and legumain can be found in the nucleus of cancer cells and there is also data showing that cathepsin L can be localized in the nucleus of embryonic stem cells." (PMID 32709152, 2020). "The results showed that the GC cancer cells cocultured with the legumain-knockdown TAMs showed significantly reduced cellular proliferation and migration." (PMID 31892854, 2020). "Both legumain and cystatins became attractive drug targets due to their relevance in different types of cancer and dementia." (PMID 29967063, 2018). "Our analysis showed that the LGMNHigh percentages in cancer tissues and normal tissues were significantly different, with values of 51.9% and 13.4% respectively, indicating that LGMN was overexpressed in tumors." (PMID 26607955, 2015). "Meta-analysis showed that legumain was overexpressed in cancer compared with in normal tissue and was higher in stage III–IV disease than in I–II disease." (PMID 26607955, 2015). "Six studies compared LGMN overexpression in well-differentiated and moderate–poorly differentiated cancers." (PMID 26607955, 2015). "The presented data enhance our knowledge on legumain biology, but further studies are warranted to elucidate the contribution of legumain processing and localization in cancer development and progression." (PMID 23326369, 2013). "The discovery of nuclear localized legumain launches an entirely novel arena of legumain biology and functions in cancer." (PMID 23326369, 2013). "This non-canonical activity becomes particularly relevant under pathophysiological conditions such as cancer and neurodegeneration, where legumain translocates to near-neutral pH environments, including the cytosol, nucleus, and extracellular space, that favor ligation over hydrolysis." (PMID 41940672, 2026). "Mechanistically, LGMN has been implicated in the activation of matrix metalloproteinases (MMP-2, MMP-3, and MMP-9), which promote extracellular matrix degradation and facilitate cancer cell invasion and metastasis." (PMID 41375125, 2025). "The reason may be that after prolegumain is secreted into the extracellular space, it is processed into mature legumain by the acidic environment outside the cells, which then exerts its cancer-promoting effects." (PMID 40227215, 2025). "Legumain is an important mammalian protease that cleaves substrates and participates in the regulation of many physiological and pathological processes, including kidney function, bone remodeling, cancer, and cardiovascular and neurodegenerative diseases." (PMID 40563290, 2025). "Consequently, LGMN-cleavable probes were designed to minimize accumulation in cells lacking LGMN while enabling the cleaved cationic peptide to selectively penetrate and accumulate in the membranes of cancer cells with high LGMN expression." (PMID 41375125, 2025). "In contrast to proliferation, apoptosis signature was significantly enriched in cancer cells from tumors harboring low LGMN expression in TAMs, indicating that LGMN might support GBM cell survival." (PMID 40131864, 2025).
cancer (continued). "Interestingly, it was found that upregulation in LGMN expression in the macrophages promoted proliferation and angiogenesis of the cancer cells under both in vitro and in vivo settings." (PMID 38980440, 2024). "The results of this study have corroborated that the prognosis of cancer patients could be related to LGMN expression, which suggest that LGMN expression can be used as a novel biomarker in predicting prognosis of cancer patients." (PMID 38980440, 2024). "LGMN is highly expressed in many cancers and appears to promote cancer progression." (PMID 37077181, 2023). "Therefore, we attempted to extract natural anti-LGMN inhibitors from marine sources and assess their efficiency in BC cells and in murine cancer models." (PMID 38139241, 2023). "The regulatory role of legumain (LGMN) was first reported in cancers in 2003." (PMID 38139241, 2023). "LGMN is an oncogenic protein, which can facilitate cancer progression and metastasis." (PMID 38139241, 2023). "As a result of stimulating the PI3K/AKT signaling pathway, LGMN may have a crucial role in the proliferation, invasion, and survival of cancer cells." (PMID 36825203, 2023). "Meanwhile, the results of autoradiography further verified that radiotracer [18F]SF-AAN could assess the expression level of legumain in cancer at in vivo level specifically and sensitively." (PMID 35631369, 2022). "Discovering the role of legumain in the pathogenesis of various diseases has initiated an approach of targeting legumain or utilizing legumain for prodrug activation, which may provide novel therapeutic opportunities for, e.g., cancer therapy." (PMID 36555634, 2022). "All the results demonstrated that [18F]SF-AAN could efficiently detect the expression level of legumain in living cancer cells." (PMID 35631369, 2022). "It is well-stated that cathepsin and legumain showed overexpression in several cancer cells." (PMID 35331246, 2022). "Therefore, it was inferred that [18F]SF-AAN was capable of distinguishing legumain-overexpressed cancer cells specifically." (PMID 35631369, 2022). "However, the MKN28 GC cancer cells cocultured with the legumain-overexpressing TAMs exhibited significantly increased cellular proliferation and migration." (PMID 31892854, 2020). "The results of studies on the clinical significance of LGMN expression in cancer are contradictory." (PMID 26607955, 2015). "Furthermore, the overall staining pattern showed elevated cytoplasmic presence of legumain in all apparent carcinoma cells compared to the stromal cells (red and blue arrow, respectively)." (PMID 23326369, 2013). "In addition to being linked to advanced disease and the spread of cancer, LGMN over expression also has a negative impact on patient outcomes." (PMID 36825203, 2023). "LD-MDS is responsively activated by legumain protease and converted into DM4-loaded exosome-like nanovesicles (DENs), facilitating efficient internalization by metastatic 4T1 cancer cells and considerable cell death." (PMID 40375976, 2025). "It has been determined that asparaginyl endopeptidase (AEP, also called legumain) is overexpressed in various cancer types and triggers the EMT process as well as metastasis via stimulating Akt and MAPK signaling pathways." (PMID 32756339, 2020). "Legumain (LGMN), a cysteine protease, regulates macrophage polarization in various cancers." (PMID 41933939, 2026). "In summary, substantial LGMN expression in various cancer tissues rather than in normal tissues can make it an ideal target for cancer treatment." (PMID 38980440, 2024). "Pro-legumain promotes cancer cell migration and invasion independent of legumain protease activity." (PMID 41294885, 2025).
cancer (continued). "In addition, we also noted that LGMN+ and SPP1+ TAMs represented more than half of the TAMs and they mostly came from patients P8/P9, the same patients with identified cancer cell cluster C6 that displayed stemness-related phenotypes." (PMID 38169544, 2024). "However, currently, no publications have identified the role of legumain in the development of canine cancers." (PMID 35203212, 2022).
infection (5 papers, 2020 to 2025). The state of being infected such as from the introduction of a foreign agent such as serum, vaccine, antigenic substance or organism. "To that end, we transduced cell lines with endogenous LGMN expression with lentiCRISPRv2 constructs encoding Cas9 plus gRNAs targeting either ACE2, TMPRSS2, or LGMN and subjected the knock-out cell lines to infection with replication competent SARS-CoV-2." (PMID 40674406, 2025). "Taken together with our in vitro data, this analysis suggests that in addition to increasing host cell susceptibility, increased expression of LGMN over the course of infection could be a marker of poorer clinical outcomes." (PMID 40674406, 2025). "In contrast, two genes belonging to HSP70 family including HSPA1s and HSPA4 as well as LGMN were constantly upregulated during infection with A. invadans." (PMID 33177569, 2020). "Notably, the cholestanol-induced increases in α-syn cleavage and hyperphosphorylation were decreased in SH-SY5Y cells after infection with lentiviral shRNA-LGMN (sh-LGMN)-mediated knocked down LGMN." (PMID 37937646, 2023). "Infection with replication competent SARS-CoV-2 demonstrated that while removal of the signal peptide or substitution with an NLS ablated LGMN’s infection promoting activity, targeting of LGMN to the cell surface (LGMN Vk) restored improved replication competent SARS-CoV-2 infection to WT levels." (PMID 40674406, 2025). "Strikingly, we found that disruption of LGMN–but not TMPRSS2–lead to significant decreases in replication competent SARS-CoV-2 infection, suggesting that LGMN acts independently of TMPRSS2 to promote infection." (PMID 40674406, 2025).
bone disorder (1 paper, 2024). "By demonstrating the role of legumain in TGF-β1-induced inhibition of osteoblast maturation, our study has important implications for bone disorders associated with aberrant TGF-β1 signaling and suggests legumain as a potential target for therapeutic interventions." (PMID 39363898, 2024).
respiratory diseases (1 paper, 2025). "Many studies have revealed that legumain plays a vital pathogenic role in various respiratory diseases." (PMID 40027188, 2025).
LGMN also shares sentences with these, for which no sentence is quoted: neurodegenerative disease (8 papers); prostate carcinoma (3); neuroblastoma (2); osteoporosis (2); pancreatitis (2); amyloidosis (1); amyotrophic lateral sclerosis (1); aortic aneurysm (1); brain infarcts (1); cerebral amyloid angiopathy (1); coronary heart disease (1); Crohn disease (1); dementia (1); diabetic nephropathy (1); endometrial tumor (1); endothelial dysfunction (1); Ewing sarcoma (1); frontotemporal dementia (1); glomerulonephritis (1); glomerulopathy (1); Harlequin ichthyosis (1); Hyperglycemia (1); Hypertension (1); hypotrichosis (1); idiopathic pulmonary fibrosis (1); immune deficiency (1); intestinal tumor (1); ischemia (1); kidney (1); kidney disease (1).
A further 20 diseases each share a sentence with LGMN in 1 paper.